IL2 (interleukin 2)
Diseases named in the same sentence as IL2 in open-access papers (continued):
Sharing a sentence is not in itself a finding about the gene and the disease.
myeloma (continued). "Furthermore, NK cells isolated from myeloma patients have been expanded with 500 IU/ml IL-2 and shown to have ex vivo killing potential against autologous tumor cells." (PMID 23724099, 2013). "Moreover, we and others showed that hypoxia can reduce effector functions of unactivated NK cells and that NK cell activation with high-dose IL-2 could restore NK cell cytotoxicity against multiple myeloma." (PMID 34203549, 2021). "To provide additional support for the hypothesis that IL-2 contributes to elotuzumab-mediated NK cell-dependent myeloma cell killing, we examined myeloma cell co-cultures either with PBL or with purified NK cells in the presence of elotuzumab and an exogenous source of IL-2." (PMID 25287778, 2015). "The combination enhanced myeloma cell killing by modulating NK cell function that coincided with the upregulation of adhesion and activation markers, including interleukin (IL)-2Rα expression, IL-2 production by CD3+CD56+ lymphocytes, and tumor necrosis factor (TNF)-α production." (PMID 25287778, 2015). "Compared with IL-2 or IL-7, IL-15 was found to increase the persistence and efficacy of CAR T cells in multiple myeloma." (PMID 36618357, 2022). "The combination of hemibodies, however, induced T cells to secrete IL-2 and interferon-γ (IFN-γ) and to efficiently lyse myeloma cells to almost the same extent as BiTE molecules, which are given as comparators." (PMID 33420283, 2021). "Pre-stimulation ex vivo of allogeneic T cells by exposure to MOPC315.BM MM cells in the presence of IL-2, anti-CD3 and anti-CD28 resulted in expansion of the myeloma-reactive T cell TCRVβ 2, 3 and 8.3 subfamilies." (PMID 31727148, 2019). "In moribund myeloma-bearing (MB) mice, we previously showed that splenic PD-1+ T cells stimulated with anti-CD3 exhibit an altered cytokine profile (i.e., secreted less IL-2, IFN-γ and TNF-α) as compared to PD-1− T cells or T cells from non-MB mice." (PMID 28642819, 2017). "Enhanced IL-2 secretion by CD3+/CD56+ cells and production of TNF-α led to enhanced killing of myeloma cells." (PMID 25287778, 2015). "Here, we demonstrate that, even though IL-2 activation enhanced degranulation of all NK cell subsets, KIR–ligand-mismatched NK cells still mediated a more potent anti-myeloma response than matched NK cells." (PMID 25920521, 2015). "Concomitant with the increase in IL-2 pathway components, functional activation of the LFA-1-ICAM-1 pathway was observed, with upregulation of CD54 on both NK cells and myeloma cells." (PMID 25287778, 2015). "In another study, it was shown that, after coincubation of NK cells from normal volunteers with myeloma cells from three different MM cell lines and fresh BM samples from nine myeloma patients, myeloma cells were susceptible to NK cell lysis, even in the absence of IL-2." (PMID 22649466, 2012). "For examples, infusion of myeloid DCs and systemic administration of IL-2 have been shown to induce and expand CD4+FoxP3+ Tregs in myeloma and renal cancer patients." (PMID 21106069, 2010). "Our results do not support the use of IL2/zoledronate such as standard maintenance treatment for patients with multiple myeloma that achieve VGPR after autologous bone marrow transplantation." (PMID 33613510, 2020). "Infusion of IL-2/Ab activated Auto-MT cells also provided a significant, albeit short-term GvM effect (MST = 44 d versus MST = 19 d, respectively; *p < 0.0001), although 100% of these mice eventually succumbed to myeloma progression." (PMID 31727148, 2019). "Using PBMC/myeloma cell co-cultures enriched in CD56+ NK cells, we examined whether lenalidomide or the elotuzumab plus lenalidomide combination induced IL-2 production." (PMID 25287778, 2015).
myeloma (continued). "Interestingly, the analysis of secreted pro-inflammatory cytokines and effector molecules showed that TIM-3-, LAG-3-, and 2B4-disrupted TCRED T cells produce higher amounts of IL-2, TNFα, sFasL and perforin compared to TCRED-IRCOMP T cells when tested with the two different multiple myeloma models." (PMID 38510235, 2024). "The clinical benefit observed in terms of TTP does not support the use of maintenance treatment with IL2/zoledronate such as treatment options in myeloma patients after autologous bone marrow transplantation, especially after that lenalidomide has become the stranded of care." (PMID 33613510, 2020). "Interestingly, the anti-SLAMF7 antibody-elotuzumab has been approved for use by Food and Drug Administration (FDA), and enhances natural killer cell activation and cancer cell killing through interleukin-2 and TNF-α pathways, significantly improving progression-free survival of multiple myeloma." (PMID 28099903, 2017). "In addition, TRAIL expression was significantly increased upon cytokine stimulation on myeloma patients' NK cells, which is in concordance with the results of previous reports demonstrating TRAIL upregulation and improved NK cell cytotoxicity upon IL-2 and/or IL-15 stimulation." (PMID 30542346, 2018). "In the absence of myeloma cells, lenalidomide and pomalidomide induce CD4+ T cell secretion of IL-2 and indirect activation of Natural Killer (NK) cells." (PMID 33746969, 2021). "In these higher levels, IL-2 increased NKG2D expression and cytotoxicity against multiple myeloma, but most of the NK cell surface receptor activity did not change." (PMID 31396523, 2019). "The first used haploidentical, KIR-ligand mismatched NK cells expanded with IL-2 and anti-CD3, demonstrating the safe engraftment of autologous stem cells with no signs of GVHD in treated myeloma patients." (PMID 30542346, 2018).
hepatocellular carcinoma (55 papers, 2010 to 2025). A malignant tumor that arises from hepatocytes. "For instance, in a rat hepatoma model, liposomal IL-2 significantly increased survival time compared to free IL-2 or saline, largely due to enhanced macrophage activation and tumor necrosis factor alpha (TNF-α) production." (PMID 40143046, 2025). "In recent years, studies on the treatment of hepatitis B or hepatocellular carcinoma with the help of mRNA technology, including the delivery of IL2 cytokines and engineered TCR-T cells, have rapidly emerged." (PMID 40006578, 2025). "Cytokine-signaling-related proteins associated with lipid rafts include, for example, IL-2 and IL-15 receptor subunits in T cells, interferon receptors and STAT1 in macrophages, STAT1 and STAT3 in hepatoma cells." (PMID 39563446, 2024). "This is in line with a study showing that IL-27 pretreatment of hepatocellular carcinoma cells resulted in lowered IL-2 production by anti-CD3/-CD28 activated T-lymphocytes." (PMID 37818353, 2023). "The combination of IL-2 and IL-21 directly enhanced the cytotoxicity of human γδT cells to hepatocellular carcinoma cells in vitro." (PMID 35747139, 2022). "We have found that exosomes derived from TAMs promote the development and progression of hepatocellular carcinoma in vivo and in vitro and these effects of exosomes were partly reversed by IL-2 treatment for TAMs." (PMID 36284632, 2022). "Relevant in vitro studies have found that interferon alpha 2a combined with IL‐2 can significantly improve the inhibitory effect on HepG2.2.15 hepatoma cells." (PMID 36381411, 2022). "We next co-cultured the ZOL and IL-2 expanded blood Vγ9Vδ2 T-cells with human hepatoma cell lines, HepG2 and HuH7, to examine for an anti-HCC response." (PMID 35296658, 2022). "This study provides a new perspective to explain the mechanism by which IL-2 inhibits hepatocellular carcinoma and implies the potential clinical value of exosomal miRNAs released by TAMs." (PMID 36284632, 2022). "These experiments indicated that the in vivo results are consistent with the in vitro results and IL-2 treatment ameliorates hepatocellular carcinoma development which was mediated by exosomes from TAMs." (PMID 36284632, 2022). "One patient with hepatocellular carcinoma was treated with a combination of interleukin-2 (IL-2) injection, BCG and melatonin." (PMID 34055652, 2021). "At the same time, it was also found in this study that the levels of Treg-related immune cytokines (IL-2, IL-10, and TGFβ) were significantly increased in mice in the hepatoma-bearing model group." (PMID 33204731, 2020). "A recombinant NDV expressing soluble IL-2 has been shown to effectively regress hepatocellular carcinoma in mice and lead to the establishment of strong immunity that completely protected the cured mice from future challenge with cancerous cells." (PMID 32316317, 2020). "Hepatocellular cancer tissues were obtained from 6 patients, Tils were expanded using IL-2, IL-2/S-15, IL-2/Akti or in combination IL-2/S-15/Akti." (PMID 31827396, 2019). "Oral administration of a S. Typhimurium Ty21a strain expressing IL-2 inhibited hepatocellular carcinoma (HCC) in mouse models." (PMID 31827064, 2019). "Our study elucidates that IL-2/S-15/Akti expanded Tils and represent a viable source for the cellular therapy for patients with hepatocellular cancer." (PMID 31827396, 2019). "TCR-transduced T cells were polyfunctional, secreting the cytokines interferon gamma, tumor necrosis factor alpha and interleukin-2, and effectively killed hepatoma cells replicating HBV." (PMID 28792537, 2017). "Shikonin, a major component of L. erythrorhizon (Zi-Cao) and Arnebia euchroma (Ruan-Zi-Cao), is effective in increasing CD3+ and CD19+ lymphocytes, and improving NK activities, lymphocyte transformation and IL-2 production in hepatoma HepA22 bearing mice." (PMID 26828466, 2016).
hepatocellular carcinoma (continued). "Many cytokines contribute to the processes of initiation and development in hepatocellular carcinoma, such as interleukin-2 (IL-2), transforming growth factor ß (TGF-ß), vascular endothelial growth factor (VEGF) and insulin growth factor-1 (IGF-1)." (PMID 23418729, 2013). "In this study, DCs from hepatocellular carcinoma (HCC) patients were co-transfected with the IL-2 gene and/or the AFP gene." (PMID 23170121, 2012). "Functional analysis demonstrates that the HCV TCR-transduced both CD4+ and CD8+ T cells produce interferon-γ, TNF-α, and to a lesser extent, IL-2 when stimulated with the peptide-loaded targets or HCV+ hepatoma cells." (PMID 20686664, 2010). "PTEN could also enhance β-catenin/MYC signaling and PD-L1 expression in HBV-expressing hepatoma cells, which leads to decreased PD-1 expression, reduces IL-2 secretion, and induces T Cell apoptosis." (PMID 36582540, 2022). "Taken together, IL-2 may modulate exosomal miRNAs from TAMs to ameliorate hepatocellular carcinoma development." (PMID 36284632, 2022). "For instance, NDV Anhinga strain expressing interleukin-2 (IL-2) could effectively inhibit the growth of hepatocellular carcinoma in vivo while rNDV-IL2-TRAIL could significantly enhance the induction of apoptosis in cancer cells." (PMID 33354412, 2020). "The combination of immunostimulatory plasmid DNA encoding IL-2 and siRNA delivered by TT-LDCP NPs targeting PD-L1 in the treatment of hepatocellular carcinoma (HCC) has also been shown to significantly increase tumor infiltration and CD8+ T-cell activation." (PMID 37138873, 2023). "Sorafenib, the targeted drug used for hepatocellular carcinoma (HCC) treatment was also found to induce mitochondrial fission, an effect amplified by IL-2 supplementation." (PMID 34485975, 2021). "By extension, if FOXP3+ Tregs showed no increase in patients with CHB and in the tumor environment after pre-treatment, sequential IL-2 therapy (combined with immune checkpoint blockade) may have an application in the eradication of tumors such as hepatocellular carcinoma." (PMID 34737296, 2021). "In hepatocellular carcinoma, female subjects were enriched with PPAR pathway, whereas males with PI3K, PI3K/AKT, FGFR, EGFR, and IL-2 signaling pathway." (PMID 36964522, 2023). "For patients with hepatocellular carcinoma, the coexpression of CD161 and IL-7R enhances IL-2, TNF-α, and perforin expression which improve prognosis." (PMID 35028320, 2022). "After removal of ZOL, hepatoma cell lines were again co-cultured with IHL and were then able to trigger a significant increase in Vγ9Vδ2 T-cell effector function (IFN-γ, TNF-α, IL-2 expression)." (PMID 35296658, 2022). "When co-incubated together with an HBV+ hepatoma cell line or HBV-infected primary human hepatocytes, HBsAg-specific CAR+ T-cells showed high levels of IFN-γ and IL-2 secretion, as well as specific lysis of infected cells." (PMID 34452428, 2021). "A number of studies demonstrating FUZHENG Yiliu’s effects on hepatoma cells have been published showing an increase in CD3+, CD4+ and NK cells in peripheral blood with an increase in IL-2 and TNF-α, thus inhibiting hepatocellular cancer proliferation." (PMID 32372963, 2020). "SBS decreases the tumor weight and increases serum interleukin 2 (IL-2), interferon-γ (IFN-γ) and tumor necrosis factor-α (TNF-α) in mice with xenografted hepatocellular cancers." (PMID 25897964, 2015). "Investigation of potential schizophrenic pathways with the IL-2/TREM-1 pathway reveals possible complexes or drugs responsible for novel treatment of schizophrenia and hepatocellular carcinoma." (PMID 24564241, 2013). "Also NDV, the Anhinga strain expressing IL-2 (NDV/Anh-IL-2), effectively inhibited the tumour growth in murine H22 hepatocellular carcinoma." (PMID 36140243, 2022). "Furthermore, co-expression of IL-2 and IL-12 on the NDV backbone led to enhanced anti-hepatoma activity in mice." (PMID 32316317, 2020).
hepatocellular carcinoma (continued). "Meanwhile, it increased NK cells’ cytotoxicity in spleen, down-regulated the amount of CD4+CD25+Foxp3+ Treg cells and Th17 cells in tumor tissue, and decreased IL-10, TGF-β, and IL-17A levels (P < 0.01) whereas increased IL-2 and IFN-γ levels (P < 0.01) in the serum of hepatoma H22-bearing mice." (PMID 28086772, 2017). "Also, CD28−Tim-3+CD4+ T cells from patients with hepatocellular carcinoma were reported to exhibit impaired ability to produce of IL-2 and IFNγ but their possible exhausted status was not ruled out." (PMID 34386013, 2021). "Importantly, CD69+CD49a+ Vγ9Vδ2 TRM isolated from the human liver displayed a greater increase in effector function (IFN-γ, IL-2 expression) compared to their non-resident (CD69−CD49a−) Vγ9Vδ2 T-cell counterparts when co-cultured with ZOL-treated hepatoma cell lines." (PMID 35296658, 2022). "Using a schizophrenia-hepatocellular carcinoma network, the authors found that some schizophrenia candidate genes (SIRPB1, SYK, and LCK) and genes mediating the immune responses in the etiology mechanism of schizophrenia (IL-2 and TREM-1/DAP12) may also function as tumor-suppressor genes." (PMID 29254248, 2017). "Our results indicate that both the HCV TCR-transduced CD4+ and CD8+ T cells recognized the HCV NS3:1073–1081 peptide-loaded targets and HCV+ hepatocellular carcinoma cells (HCC) in a polyfunctional manner with cytokine (IFN-γ, IL-2, and TNF-α) production as well as cytotoxicity." (PMID 20686664, 2010).
prostate carcinoma (55 papers, 2001 to 2025). A carcinoma that arises from epithelial cells of the prostate gland. "In prostate tissue, inflammation has been linked to the production of interleukin-6 (IL-6) and interleukin-2 (IL-2), cytokines strongly implicated in prostate-cancer pathogenesis." (PMID 41375042, 2025). "Consistent with our previous observations using low doses of a gnetin C-supplemented diet in a high-risk PIN model of prostate cancer, our current study demonstrated that gnetin C was able to reduce the levels of IL-2 compared to the vehicle." (PMID 38611022, 2024). "To date, a single prostate cancer association study has investigated genetic variants within IL-2 for prostate cancer risk and revealed a significant contribution of a synonymous IL-2 exon 1 variant (rs2069763) to disease susceptibility." (PMID 20184734, 2010). "The observation that MMTSO causes an upregulation in IL‐2 signaling gene sets provides evidence that MMTSO could beneficially affect immunomodulatory processes within the context of prostate cancer and warrants further investigation." (PMID 40059483, 2025). "In prostate cancer, metformin was reported to induce the suppression of pro-inflammatory cytokines IL-2, TNF-α, and INF-ɣ, which was correlated with the inhibition of the mTOR Pathway." (PMID 37842429, 2023). "Other inflammatory cytokines with demonstrated reduction after ADT in prostate cancer patients include IL-1β, IL-2, tumor necrosis factor (TNF)-α, and interferon (IFN)-γ." (PMID 34926085, 2021). "For functional analysis, CAR T cells were co-cultured with prostate cancer cells and analyzed for IL-2 secretion, CD25 expression, and cell proliferation." (PMID 31677604, 2020). "IL-2 secretion was monitored as an activation marker after the exposure of engineered Jurkat cells to prostate cancer cells." (PMID 31677604, 2020). "Our data uncovered the novel role of IL‐2 in prostate cancer cells, and its knockdown evidently exerted antitumor action, which positioned itself as a potential target for therapeutic interventions." (PMID 31981447, 2020). "For checking the function and activity of NBPII-CAR in Jurkat cells, engineered Jurkat cells were co-incubated with prostate cancer cells in different ratios and IL-2 production, CD25 expression and proliferation were assessed." (PMID 31677604, 2020). "Next, we wished to assess the influence of CTV-1 priming and IL-2 (100 U/ml) activation on the cytotoxicity of NK cells isolated from thawed PBMC preparations derived from patients with prostate cancer against PC3 and K562 cells." (PMID 30761160, 2018). "Our work broadened the medicinal applications of rTCS and the combination of rTCS with IL-2 serves as a novel strategy against human prostate cancer." (PMID 27015938, 2016). "And rTCS combined with IL-2 is a promising strategy in treating patients with prostate cancer in future." (PMID 27015938, 2016). "Our analysis indicated that Treg depletion had a higher efficacy than IL-2 neutralization as an adjuvant therapy in the treatment of prostate cancer." (PMID 26868634, 2016). "Currently, cytokines are the most involved in prostate cancer immunotherapy such as interleukin-2 (IL-2) and granulocyte macrophage colony-stimulating factor (GM-CSF)." (PMID 26246000, 2015). "Seventeen patients with recurrent prostate cancer received continuous low-dose subcutaneous IL-2 (1.2 × 106 IU/m2/day) daily for 8 weeks with weekly intravenous infusions of J591 (25 mg/m2) during weeks 4–6." (PMID 21811498, 2012). "The variant rs3136534 in the IL2 3' untranslated region (UTR) however, displayed a marginally significant association with risk for prostate cancer." (PMID 20184734, 2010). "Alternatively lower doses of IL-2 for treatment of common malignancies including prostate cancer contributes to an anti-tumor immune response via activation of tumor specific NK cells." (PMID 20184734, 2010).